DMD (dystrophin)
Diseases named in the same sentence as DMD in open-access papers (continued):
Sharing a sentence is not in itself a finding about the gene and the disease.
muscular dystrophy (continued). "The excess fibrotic deposition in muscular dystrophy is best characterized for dystrophin-mediated muscular dystrophy." (PMID 37746696, 2023). "Taken together, these results suggest that single-swap editing can cause exon skipping and efficiently restore production of an internally truncated, but partially functional, dystrophin protein that ameliorates pathological features of muscular dystrophy." (PMID 37215149, 2023). "Based on a systemic review of patients with muscular dystrophies from 1960 to 2013 across the world, dystrophin-related muscular dystrophies were found to be the second most prevalent type of muscular dystrophy." (PMID 37626915, 2023). "In dystrophin-associated cardiomyopathies, i.e. Duchenne (DMD) and Becker (BMD) Muscular Dystrophies, caused by the absence or the decreased expression of full-length dystrophin, respectively, the sarcolemma becomes fragile and susceptible to damage." (PMID 36419836, 2022). "This produces a truncated dystrophin protein in DMD patients that theoretically leads to milder symptoms of muscular dystrophy similar to BMD patients." (PMID 35935842, 2022). "Mutations in the dystrophin gene lead to complete absence or partial production of dystrophin protein, giving rise to Duchenne (DMD) and Becker (BMD) muscular dystrophy, respectively." (PMID 35681116, 2022). "This HTS assay establishes feasibility for the discovery of small-molecule modulators of the actin–dystrophin interaction, with the ultimate goal of developing therapies for muscular dystrophy." (PMID 36372234, 2022). "Dystrophin is most comprehensively studied in the skeletal muscle due to serious symptoms found related to the skeletal muscle of patients with muscular dystrophy." (PMID 36505053, 2022). "New advances in gene therapy and understanding of dystrophin (DYS) expression in other muscular dystrophies have opened new opportunities for treatment." (PMID 36539515, 2022). "LncRNA H19 reportedly ameliorates muscular dystrophy by suppressing the degradation of the dystrophin protein." (PMID 36619896, 2022). "Previous reports have shown that restoration of around 15% of normal levels of dystrophin is sufficient to protect muscle from contraction-induced injury and 30% to avoid muscular dystrophy in humans." (PMID 35563191, 2022). "With the development of several potential gene therapies for treating DMD and other muscular dystrophies, there is a growing need for reliable and quantitative methods to assess dystrophin (DYS) expression in impacted muscle tissues in the clinic." (PMID 36539515, 2022). "Duchenne is the most common type of muscular dystrophy and is caused by frame-shifting mutations in the DMD gene that prevent the full translation of its protein product, dystrophin." (PMID 35067193, 2022). "A muscle biopsy indicated many degenerating and regenerating fibers with endomysial fibrosis, consistent with muscular dystrophy, but the immunohistochemical study showed normal dystrophin expression." (PMID 36209187, 2022). "Recently, in muscular dystrophy (MD) patients, H19 was found to directly interact with dystrophin and inhibit E3-ligase-dependent polyubiquitination at Lys3584 for protein degradation." (PMID 34604357, 2021). "Many muscular dystrophy therapeutic interventions aim to restore or partially restore dystrophin expression." (PMID 33441839, 2021). "Duchenne (DMD) and Becker (BMD) muscular dystrophy are the most common forms and are characterized by an absence or decreased expression of dystrophin." (PMID 33441839, 2021). "For example, DAG1 is a pivotal component of the dystrophin-glycoprotein complex and its dysfunction is related to many muscular dystrophies, amongst other diseases." (PMID 34046427, 2021). "We previously reported that the lncRNA H19 regulates the poly-ubiquitination and protein stability of dystrophin (DMD) in muscular dystrophy." (PMID 34454586, 2021).
muscular dystrophy (continued). "DOT1L-specific depletion in cardiomyocytes triggers the total depletion of H3K79me2/3 and finally the reduction of the dystrophin (DMD) gene, a membrane-associated protein involved in dilated cardiomyopathy and muscular dystrophy." (PMID 34568453, 2021). "Of note, the proteins encoded by genes linked to other muscular dystrophies such as COL6A1, CAV3, DYSF, DMD, TTN, and VCP and the strongest family sequencing candidates INTS1 and ANK2 were all found in nuclear envelope proteomics datasets." (PMID 31862442, 2020). "Perturbation of dystrophin and dystroglycan in photoreceptor cells led to disrupted axon guidance, similar to neuronal defects seen in human muscular dystrophy patients." (PMID 33080928, 2020). "Muscular dystrophy is caused by a frameshift mutation in the DMD gene, which encodes dystrophin, a protein in muscle cells that connects the cytoskeleton with the cell membrane." (PMID 32575461, 2020). "Taking DMD as an example, the ICD-9 code refers to muscular dystrophy in general, which includes but is not limited to DMD (ICD9-CM code: 359.1)." (PMID 32503598, 2020). "In DMD patients, it has been shown that 30% dystrophin levels were sufficient to prevent muscular dystrophy." (PMID 32717791, 2020). "This boy has intermediate muscular dystrophy phenotypes, indicating that even low levels of dystrophin can mitigate skeletal muscle weakness." (PMID 32717791, 2020). "Impaired mitochondrial function was revealed in dystrophic mouse models including, the muscular dystrophy (mdx) and the double knockout dystrophin strains." (PMID 32612995, 2020). "In mice, the ablation of PTRH2 alone produces a more severe and lethal myopathy similar to the muscular dystrophy phenotype found in the double knockout of dystrophin and integrin α7β161." (PMID 33298880, 2020). "The name ‘dystrophin’ was introduced in this paper (derived from ‘muscular dystrophy’), and this name was then broadly adopted." (PMID 32608079, 2020). "On the other hand, the role of gene DMD, long known for its intrinsic relationship with muscular dystrophies, has previously been addressed in lung and breast cancer." (PMID 31766738, 2019). "Dystrophin is responsible for the maintenance of plasma membrane stability, and its absence leads to muscular dystrophy." (PMID 31162948, 2019). "The DMD KO rabbits displayed typical muscular dystrophy signs, as evidenced by increased fiber size variation, centrally nucleated fibers, fibrosis and fatty replacement." (PMID 29871865, 2018). "In skeletal muscle, DG is part of the dystrophin-glycoprotein complex that is crucial for sarcolemma stability and it is involved in a plethora of muscular dystrophy phenotypes." (PMID 29157305, 2017). "The present study suggests that the IL-1β/Jagged1 pathway will be a new therapeutic target to ameliorate exacerbation of muscular dystrophy in a dystrophin-independent manner." (PMID 29194448, 2017). "Genetic disruption of the dystrophin complex produces muscular dystrophy characterized by a fragile muscle plasma membrane leading to excessive muscle degeneration." (PMID 29065150, 2017). "Accordingly, dystrophin-deficient mdx mice treated with BGP-15, a Hsp72 activator, showed improved muscular dystrophy phenotype." (PMID 28947997, 2017). "iPSCs-derived MPCs exert strong therapeutic effects on muscular dystrophy by restoring dystrophin expression and acetylcholine receptor distribution." (PMID 28979820, 2016). "Evidence of utrophin-independent reduction in muscular dystrophy pathology was demonstrated recently by crossing a transgenic PGC-1α mouse to the severely affected dystrophin/utrophin double knockout mouse." (PMID 27430020, 2016). "MyHC fiber type analyses were recently reported in a non-dystrophin DGC muscular dystrophy, namely the Fktn-deficient model of dystroglycan glycosylation-deficient muscular dystrophy." (PMID 27430020, 2016).
muscular dystrophy (continued). "For instance, in the case of DMD, the maximal effect that can be reached using an exon skipping strategy is the milder Becker's Muscular Dystrophy phenotype due to the expression of a truncated dystrophin protein, and this is still a serious condition." (PMID 27623443, 2016). "It is the most common and severe form of muscular dystrophy where there is failure to manufacture dystrophin." (PMID 26379389, 2015). "Mini-dystrophin rAAV9 administered intravenously in golden retriever muscular dystrophy (GRMD) dogs revealed varied dystrophin expression (between 15% and 100% depending on the muscle analyzed) and was also present in the heart." (PMID 25988613, 2015). "DMDmdx-βgeo mice constitute a model of muscular dystrophy where dystrophin, a major component of the architecture of the myofiber, is lacking." (PMID 26503169, 2015). "The third example relates to aberrations in three genes that separately cause different subtypes of muscular dystrophy: dystroglycan 1 (DAG1), dystrophin (DMD), and caveolin 3 (CAV3)." (PMID 24921629, 2014). "The most common and severe form of muscular dystrophy is Duchenne muscular dystrophy (DMD), caused by the mutation or deletion of the Dmd gene that encodes the structural protein dystrophin." (PMID 23671652, 2013). "In fact, DMD mutant male piglets showed severe muscular dystrophy already at birth, and a proportion died shortly later." (PMID 23688045, 2013). "The interaction partners of Dg and dystrophin, as well as the Dg–dystrophin signaling are extensively studied in mammalian muscle cell culture and in muscle tissue, as well as on the Drosophila muscular dystrophy model." (PMID 24427166, 2013). "These animals lack dystrophin and they exhibit many signs of muscular dystrophy, such as repetitive cycles of degeneration and regeneration of muscle fibers." (PMID 22815846, 2012). "Nevertheless, the amount of the B dystrophin transcript is still sufficient to guarantee protein levels (57% in LT and 29% in SA) able to avert muscular dystrophy, as we have previously reported." (PMID 22455600, 2012). "Mutations in the DMD gene, which encodes dystrophin, mostly result in the deletion of one or several exons and cause Duchenne (DMD) and Becker (BMD) muscular dystrophies." (PMID 22776072, 2012). "Definitive skeletal muscle treatment for muscular dystrophy will then likely require restoration of the dystrophin protein complex in all affected muscle groups." (PMID 24524008, 2012). "The fly genome has many of the components of the vertebrate dystroglycan complex and reflecting this, flies with decreased levels of DG or dystrophin develop a progressive muscular dystrophy." (PMID 20463973, 2010). "James Ervasti and colleagues show that injection of a truncated form of utrophin transduced all tissues examined, integrated with members of the dystrophin complex, and reduced serum levels of creatine kinase in a mouse model of muscular dystrophy." (PMID 19478831, 2009). "Three genes were chosen from a group of human retinal disease genes: C3 (already included), dystrophin, muscular dystrophy (DMD) and PRP3 pre-mRNA processing factor 3 (Prpf3)." (PMID 18989387, 2008). "Mutations in the DMD gene result in a defective or nonfunctional Dystrophin protein, which causes a group of muscle-wasting disorders known as muscular dystrophies." (PMID 39981262, 2025). "In addition to dystrophin, various transgenes have also been investigated in gene replacement clinical trials for muscular dystrophies." (PMID 39949979, 2025). "BMD is a milder form of muscular dystrophy associated with reduced but not absent dystrophin and has a later onset and slower progression." (PMID 41300820, 2025). "While most investigations into muscular dystrophy have focused on the role of Dystrophin within muscles, it is unclear whether a muscle-specific role of Dystrophin underlies the pre- and post-synaptic defects seen here." (PMID 38812789, 2024).
muscular dystrophy (continued). "It is the most common of the childhood muscular dystrophies and results from the lack of the membrane-associated protein, dystrophin, which is critical for proper force transmission in muscle cells." (PMID 38713520, 2024). "CA3, another carbonic anhydrase, known as a recurrent serum marker in dystrophin deficient muscular dystrophy, was not significantly dysregulated in serum derived of our patients." (PMID 38652110, 2024). "Muscular dystrophy patients may show on muscle biopsy a secondary reduction in some of the DGC proteins or of dystrophin itself." (PMID 39408683, 2024). "Since a KD was shown to improve muscle structure and function in a rat model of muscular dystrophy, a KD may improve muscle strength in part by increasing dystrophin levels and improving force transfer in this model of CAC." (PMID 37445930, 2023). "Female carriers of dystrophin gene mutations (DMD-FC) were previously considered non-manifesting, but in recent decades, cardiomyopathy associated with muscular dystrophy and myocardial fibrosis has been described." (PMID 37697356, 2023). "More recently, a clinical and genetic neuromuscular cohort analysis on Lebanese patients performed from 1999 to 2019 showed that dystrophin-related muscular dystrophies are also the second most frequently diagnosed inherited neuromuscular disorders associated with the highest number of variants." (PMID 37626915, 2023). "From a psychological and psychiatric point of view, patients with muscular dystrophy are frequently associated with comorbidities caused by the disease itself, owing to the absence of cerebral dystrophin, as well as the devastating impacts of the disease." (PMID 37371191, 2023). "From the overall cohort, 343/623 (55%) rare disease patients; [Muscular Dystrophy- 65%; (DMD n= 139, BMD n= 11), SCA type 1‐3 ‐ 53% (SCA1 n= 61,SCA2 n= 23, SCA3 n= 39), HD- 52% (n= 45) and SMA- 34% (n= 22)] were positive for initial molecular diagnostics by MLPA and single plex PCR." (PMID 36819775, 2023). "Additional cluster 3 proteins categorized to cardiomyopathy and sarcomeric proteins exposed to constant mechanical stress, including Desmin (DES), dystrophin muscular dystrophy (DMD); myosin binding protein C, cardiac (MYBPC3); myosin light polypeptide 2 (MYL2); Titin (TTN) and phospholamban (PLN)." (PMID 36681760, 2023). "Lack of dystrophin causes muscular dystrophy and atrophy, with increased central nuclei, regenerating fibers, necrotic fibers, macrophage infiltration, and fibrosis." (PMID 35977948, 2022). "This review highlights that there is a major need for more research investigating the role of dystrophin in vascular smooth muscle, which could ultimately add to therapeutics for muscular dystrophies." (PMID 36505053, 2022). "Resveratrol, an activator of SIRT1, ameliorates muscular function in muscular dystrophy patients and dystrophin-deficient mdx mice, although its mechanism is still not fully elucidated." (PMID 36097021, 2022). "Immunohistochemical testing revealed the absence of dystrophin, confirming the diagnosis of dystrophin-deficient muscular dystrophy." (PMID 36359052, 2022). "As with dystrophin, mutations that lead to loss or defects in the other components of dystrophin-glycoprotein complex and DGC-associated proteins also promote different forms of muscular dystrophy." (PMID 34298968, 2021). "(d) Reflex to other muscular dystrophy-causing genes in the setting of persistently elevated CK but no DMD variant detected." (PMID 34842620, 2021). "Furthermore, the EV associated CP05 anchored ASO was functionally active in increasing dystrophin in a muscular dystrophy mouse mode which provides another avenue of passive EV loading." (PMID 34527423, 2021). "An apparent short isoform of dystrophin and associated glycoproteins were identified in spleen by mass spectrometry but appear not be affected in muscular dystrophy." (PMID 32916630, 2020).
muscular dystrophy (continued). "In particular, recent gene editing methods that led to the restoration of dystrophin expression in a canine model of muscular dystrophy could be applied to other canine models such as this before translation to humans." (PMID 31772832, 2019). "SSPN is able to reduce the pathology of muscular dystrophy in the DMD murine model by increasing membrane localization of the UGC and α7β1D-integrin adhesion complexes, effectively increasing laminin binding to compensate for the loss of dystrophin." (PMID 31831063, 2019). "Therefore, the DMD KO rabbit can be used in preclinical studies to evaluate the therapeutic effects of the tested medicine or treatment on muscular dystrophy and cardiomyopathy." (PMID 29871865, 2018). "There is no cure to date for muscular dystrophies caused by absent or malfunctioning Dystrophin, be it lethal Duchenne or milder Becker type." (PMID 29399383, 2017). "The IL-1β/Jagged1 pathway may be a new therapeutic target to ameliorate exacerbation of muscular dystrophy in a dystrophin-independent manner." (PMID 29194448, 2017). "The large number of altered proteins belonging to the dystrophin complexome supports the findings from previous comparative proteomics studies and suggests a number of robust and universal biomarkers of muscular dystrophy." (PMID 26793286, 2016). "However, relatively normal immunohistochemistry findings with an anti-dystrophin antibody clearly showed that the muscular dystrophy in the Landseer dogs is different from the Duchenne/Becker type." (PMID 26438297, 2015). "Dystrophin was first studied as a protein connected to muscular dystrophy." (PMID 26230713, 2015). "Increased levels of IL-6 induced, in mdx/IL6 mice, the severe features and progressive nature of human DMD, in a stage normally spared by the absence of dystrophin, suggesting that IL-6 is causally linked to the pathogenesis of muscular dystrophy." (PMID 26251044, 2015). "Thus, the transcriptional response of the myosin chaperone genes in myosin folding myopathy is in sharp contrast to the dystrophin response in muscular dystrophy." (PMID 26631063, 2015). "Here, we have tried to address this issue in the field of muscular dystrophy research by employing sensitive label-free mass spectrometry for the unequivocal identification of the full-length Dp427 isoform of dystrophin in total tissue extracts from hind limb homogenates in a comparative study." (PMID 28248273, 2015). "In dystrophin deficient muscular dystrophy (DD-MD) the absence of dystrophin results in damage to the muscle." (PMID 26401335, 2015). "Large neuromuscular clinics also see increasing numbers of wheelchair-dependent children and adolescents most of whom develop a progressive scoliosis with other disorders, such as the myopathies, non-dystrophin-related muscular dystrophies, and Friedreich ataxia." (PMID 24728975, 2014). "We find that the muscle degeneration observed in a C. elegans model of dystrophin-based muscular dystrophy can be suppressed by clp-1 inactivation and that nemadipine-A inhibition of the EGL-19 calcium channel reveals that Ca2+ dysfunction underlies the C. elegans MyoD model of myopathy." (PMID 22479198, 2012). "However, a female carrier who had 45% protein level dystrophin expression on western blot was found with severe muscular dystrophy." (PMID 21187970, 2010). "Mutations in the DGC cause muscular dystrophies; however only mutations in Dystrophin, but not Dystroglycan per se, are associated with known types of muscular dystrophies in vertebrates." (PMID 19250553, 2009). "We report a girl with a de novo deletion at Xp21.2 on the maternal chromosome, including DAX1, the GK gene and 3′ end of the dystrophin gene, who presented with salt losing adrenal insufficiency and moderate developmental delay, but relatively mild features of muscular dystrophy." (PMID 18762570, 2008).